TBL1XR1 (TBL1X/Y related 1)
Description:
F-box-like protein involved in the recruitment of the ubiquitin/19S proteasome complex to nuclear receptor-regulated transcription units. Plays an essential role in transcription activation mediated by nuclear receptors. Probably acts as integral component of the N-Cor corepressor complex that mediates the recruitment of the 19S proteasome complex, leading to the subsequent proteasomal degradation of N-Cor complex, thereby allowing cofactor exchange, and transcription activation.
Synonyms: IRA1; TBLR1; FLJ12894; C21; DC42; MRD41
Tractability: PROTAC: UniProt records ubiquitination sites on it; ubiquitination databases record sites on it; its protein half-life has been measured.
Target class: Reader; Epigenetic regulator; Methyl-lysine/arginine binding protein; WDR domain
Gene: Protein-coding gene on chromosome 3 (177,019,340 to 177,228,000, reverse strand). Ensembl gene ENSG00000177565.
Subcellular location: Nucleus
Subcellular location (Human Protein Atlas): Nucleoplasm
Pathways (Reactome):
Disease: Constitutive Signaling by NOTCH1 HD+PEST Domain Mutants; Constitutive Signaling by NOTCH1 PEST Domain Mutants; HCMV Early Events
Circadian clock: BMAL1:CLOCK,NPAS2 activates circadian expression; Expression of BMAL (ARNTL), CLOCK, and NPAS2; RORA,B,C and NR1D1 (REV-ERBA) regulate gene expression
Gene expression (Transcription): MLL4 and MLL3 complexes regulate expression of PPARG target genes in adipogenesis and hepatic steatosis; Notch-HLH transcription pathway
Metabolism: Activation of gene expression by SREBF (SREBP); PPARA activates gene expression; Regulation of lipid metabolism by PPARalpha
Cellular responses to stimuli: Cytoprotection by HMOX1; Heme signaling
Developmental Biology: Differentiation of naive CD4+ T cells to T helper 2 cells (Th2 cells); Transcriptional regulation of white adipocyte differentiation
Signal Transduction: NOTCH1 Intracellular Domain Regulates Transcription; NR1H3 & NR1H2 regulate gene expression linked to cholesterol transport and efflux
Chromatin organization: HDACs deacetylate histones
Organelle biogenesis and maintenance: Transcriptional activation of mitochondrial biogenesis
Gene Ontology:
Molecular function: beta-catenin binding; histone binding; protein binding; transcription cis-regulatory region binding; transcription corepressor activity; DNA binding
Biological process: negative regulation of transcription by RNA polymerase II; positive regulation of canonical Wnt signaling pathway; positive regulation of DNA-templated transcription; positive regulation of transcription by RNA polymerase II; proteasome-mediated ubiquitin-dependent protein catabolic process; regulation of transcription by RNA polymerase II
Cellular component: histone deacetylase complex; mitotic spindle; nucleus; transcription repressor complex; nucleoplasm
Genetic constraint (gnomAD): Loss-of-function variants: 4 observed, 52.67 expected, observed/expected ratio (o/e) 0.0759, 90% interval 0.036 to 0.17. The upper end of that interval is the gene's LOEUF score, 0.17, which puts it in group 1 of 6, group 1 being the genes least tolerant of losing a copy. Missense variants: 220 observed, 564.5 expected, observed/expected ratio (o/e) 0.39, 90% interval 0.35 to 0.44. Synonymous variants: 199 observed, 191.38 expected, observed/expected ratio (o/e) 1.04, 90% interval 0.93 to 1.17.
Gene-disease validity (ClinGen):
ClinGen rates the evidence that TBL1XR1 causes each of these diseases.
complex neurodevelopmental disorder (autosomal dominant): Definitive. A disorder that involves more than one phenotype associated with the central nervous system, including but not limited to intellectual disability, autism, and seizures (epilepsy).
Cancer hallmarks: invasion and metastasis (promotes); proliferative signalling (promotes); suppression of growth (promotes)
Homologues: Orthologues: chimpanzee TBL1XR1 (99% identical), rabbit TBL1XR1 (99% identical), rat Tbl1xr1 (99% identical), dog TBL1XR1 (99% identical), mouse Tbl1xr1 (99% identical), tropical clawed frog tbl1xr1 (98% identical), macaque TBL1XR1 (97% identical), pig TBL1XR1 (97% identical), guinea pig TBL1XR1 (96% identical), zebrafish tbl1xr1b (93% identical), zebrafish tbl1xr1a (77% identical), Drosophila melanogaster ebi (76% identical). Paralogues in human: TBL1X (88% identical), TBL1Y (86% identical).
Diseases named in the same sentence as TBL1XR1 in open-access papers:
TBL1XR1 is named in the same sentence as 86 diseases in open-access papers, as found by Europe PMC text mining. Sharing a sentence is not in itself a finding about the gene and the disease. The quoted sentences say what the papers report.
prostate carcinoma (14 papers, 2016 to 2026). A carcinoma that arises from epithelial cells of the prostate gland. "Conversely, gene amplifications of TBL1XR1 were found to be associated with prostate cancer progression." (PMID 40074836, 2025). "CRISPR screen experiments identified TBL1XR1 as a candidate gene associated with PARP inhibitor resistance in prostate cancer cells." (PMID 38347836, 2024). "Here, we found that TBL1XR1 deficiency sensitizes prostate cancer cells to PARPi through decreasing γH2AX foci formation near the DNA damage sites during S phase of the cell cycle." (PMID 36523978, 2022). "They find that gains of NAALADL2 and TBL1XR1 in this locus are associated with more aggressive subtypes of prostate cancer and the transcription of pro-proliferative signalling processes." (PMID 32796921, 2020). "For example, TBL1XR1, one of the significantly up-regulated E3 across 12 cancer types, has been reported to be associated with the progression and clinical prognosis of various human malignancies, such as human non-small cell lung cancer prostate cancer, extranodal lymphoma, and gastric cancer." (PMID 39062881, 2024). "Among protein nodes, QKI, YOD1, and TBL1XR1 were the most connected, with 19, 15, and 14 edges, respectively (which ranks potential biomarkers and their impacts in prostate cancer)." (PMID 41598250, 2026). "In prostate cancer cell lines, stable ectopic expression of TBL1XR1 was shown to inhibit tumor progression via enhancing AR genes, which exhibit anti-proliferative capabilities." (PMID 40074836, 2025). "According to the TCGA database, one study found that TBL1XR1 gene gains or amplifications were more prevalent in aggressively malignant subtypes of prostate cancer than in primary cohorts." (PMID 38347836, 2024). "The oncogenic or tumor suppressive role of TBL1XR1 in prostate cancer was to be further investigated." (PMID 38347836, 2024). "In prostate cancer cells, TBL1XR1 played an essential role in AR-mediated transcription and there was physical interaction between TBL1XR1 and AR." (PMID 38347836, 2024). "Here we identified TBL1XR1 as one factor contributing to PARPi sensitivity in prostate cancer cells." (PMID 36523978, 2022). "Using publicly-available cancer genomic data we report that NAALADL2 and TBL1XR1 gains/amplifications are more prevalent in aggressive sub-types of prostate cancer when compared to primary cohorts." (PMID 32796921, 2020). "In this study we present evidence that somatic copy-number gains in NAALADL2 and TBL1XR1 are more frequent in high grade and aggressive forms of prostate cancer." (PMID 32796921, 2020). "The effects of TBL1XR1 in prostate cancer (PC) have been noteworthy, nuclear TBLR1 acted as a tumor suppressor in PC." (PMID 28977891, 2017). "However, in another study, nuclear TBL1XR1 expression was markedly reduced in both prostate cancer cells and human tumor samples compared with benign prostate cells or adjacent benign prostatic glands." (PMID 38347836, 2024). "To further understand better of PARPi response in prostate cancer, in this study, we performed a genome-wide CRISPR screen in prostate cancer cells with 3D culture condition and identified TBL1XR1 as a factor regulating sensitivity to PARPi in prostate cancer cells." (PMID 36523978, 2022). "One of these genes, TBL1XR1, regulates sensitivity to PARPi in prostate cancer cells." (PMID 36523978, 2022). "TBL1XR1 is thought to regulate the expression of nuclear hormone receptor co-repressor, and tissue types in which the TBL1XR1::PIK3CA fusions were found (invasive breast carcinoma and prostate cancer) are hormonally regulated." (PMID 41123735, 2025). "Using a multicolor fluorescence in situ hybridization approach, the copy number alterations of six genes known to be involved in aggressive prostate cancer (PTEN, MYC, MEN1, PDGFB, CTTNBP2, and TBL1XR1) was explored in a group of recurrent and in a group of nonrecurrent prostate cancer patients." (PMID 31366128, 2019).
breast carcinoma (10 papers, 2014 to 2025). "In human breast cancer tissues, Cyclin D1 and β-catenin expression were positively linked with TBL1XR1 expression." (PMID 38347836, 2024). "A recent review identified 12 different cancers, including breast cancer, which implicate TBL1XR1 in cancer progression." (PMID 41373732, 2025). "For TGFB2-dependent biomarkers, elevated TGFB2 mRNA expression is a prognostic biomarker associated with breast cancer patients that is correlated with improved OS outcomes at high expression levels of GDAP1, TBL1XR1, RNFT1, HACL1, SLC27A2, NLE1, and TXNDC16." (PMID 41373732, 2025). "Significantly higher nuclear TBL1XR1 expression instead of cytoplasm TBL1XR1 was observed in the breast cancer malignant glands compared to the adjacent benign breast glands." (PMID 38347836, 2024). "In breast cancer tissues, TBL1XR1 expression was related with proliferation marker Ki67, indicating its important role in cell proliferation." (PMID 38347836, 2024). "TBL1XR1 also promoted breast cancer and gastric cancer cell colony formation and tumor expansion in a xenograft model." (PMID 38347836, 2024). "TBL1XR1 was found to be overexpressed in breast cancer tissues and cells when compared to healthy controls." (PMID 38347836, 2024). "Kadota and colleagues observed that TBL1XR1 levels are amplified in breast cancer, and the protein plays an oncogenic role in breast cancer progression." (PMID 25145705, 2014). "In breast cancer, TBL1XR1 was correlated with clinical stage, tumor classification, node classification, metastasis classification, and histological grade, and higher TBL1XR1 expression was an independent prognostic indicator for overall survival." (PMID 41373732, 2025). "Recently, TBL1XR1 is reported to be overexpressed in multiple malignancies and contributes to carcinogenesis and tumor progression, including esophageal squamous cell cancer, cervical cancer, breast cancer, nasopharyngeal cancer, and hepatocellular carcinoma." (PMID 27672238, 2016). "In breast cancer cells, Wnt/β-catenin target genes (MYC, CD44, CYR61, Snail, AXIN2, RUNX2, LEF1, NRCAM) were significantly increased after TBL1XR1 overexpression, but decreased after TBL1XR1 knockdown." (PMID 38347836, 2024). "In breast cancer, gastric cancer and LUSC cells, ectopic overexpression of TBL1XR1 increased cell proliferation and TBL1XR1 silencing inhibited the proliferative capacity." (PMID 38347836, 2024). "As a biomarker of breast cancer stem cells, USP44 interacts directly with the WD40 motif‐containing proteins, such as the N‐CoR component, TBL1XR1, which is highly expressed in breast cancer cells." (PMID 32394588, 2020). "A number of the identified CD47-dependent genes including MBP1, TBL1XR1, girdin, cyclin D1, CDC27, SPAG9, and JAK1 have reported functions in breast cancer progression." (PMID 26840086, 2016). "In cases dependent on TGFB2, increased mRNA expression of TGFB2 alongside higher levels of GDAP1, TBL1XR1, RNFT1, HACL1, SLC27A2, NLE1, or TXNDC16 was correlated with improved OS among breast cancer patients, of which four genes were upregulated in tumor tissues (SLC27A2, TXNDC16, TBL1XR1, GDAP1)." (PMID 41373732, 2025). "Interestingly, in GC, colorectal cancer, and breast cancer besides ESCC, analysis of datasets from GEO showed that TBL1XR1 levels were significantly correlated with VEGF-C expression, and silencing TBL1XR1 resulted in decrease in VEGF-C expression." (PMID 27672238, 2016).
gastric cancer (9 papers, 2016 to 2024). A primary or metastatic malignant neoplasm involving the stomach. "Upregulated TBL1XR1 in gastric cancer has been linked to a progressed clinical phase, growing lymph node numbers and metastasis of lymph node." (PMID 38347836, 2024). "In another study, by directly targeting and reducing TBL1XR1 expression, miR-130a-3p reduced the malignant behavior of gastric cancer cells." (PMID 38347836, 2024). "Another research in gastric cancer also indicated that TBL1XR1 knockdown reversed resistance to cisplatin in vitro and in vivo." (PMID 38347836, 2024). "Another study reported that 61.2% gastric cancer tissues and 29.8% nearby normal tissues can be detected for TBL1XR1 expression." (PMID 38347836, 2024). "In gastric cancer cell lines, TBL1XR1 expression was also evaluated when compared to the normal gastric epithelial cell line." (PMID 38347836, 2024). "In both the gastric cancer tissues and cancer cell lines, TBL1XR1 and pERK1/2 expression levels showed a positive correlation." (PMID 38347836, 2024). "For instance, some studies have reported that TBL1XR1 promotes CSCs properties and metastasis in gastric cancer." (PMID 35951366, 2022). "In gastric cancer cells, miR-130a-3p inhibited cell migration and invasion via inhibiting the TBL1XR1-mediated EMT process." (PMID 36438895, 2022). "Further, miR-130a was found to downregulate TBL1XR1-mediated cell migration and invasion in gastric carcinoma." (PMID 35187064, 2021). "High expression of TBL1XR1 protein was detected in 204 of 334 (60.1%) primary gastric cancer tissues and 19 of 30 (63.3%) lymph node metastasis lesions while 18 of 20 (90.0%) adjacent nontumor mucosae showed only low expression (P < 0.001, P < 0.001, resp)." (PMID 27672238, 2016). "Samples with staining index ≥8 (median score of TBL1XR1 expression in the gastric cancers) were determined as high expression and samples with staining index <8 were determined as low expression." (PMID 27672238, 2016). "In conclusion, our study showed that TBL1XR1 is overexpressed in gastric cancer in mRNA and protein level." (PMID 27672238, 2016). "TBL1XR1 mRNA expression was analyzed in gastric cancer using a microarray dataset (GSE2701) from the Gene Expression Omnibus (GEO)." (PMID 27672238, 2016). "In mouse organoids of gastric cancer, TBL1XR1 knockdown reduced EMT and inhibited lung metastasis." (PMID 38347836, 2024). "Additionally, after TBL1XR1 knockdown in gastric cancer cells, mesenchymal cell markers expression dropped while the epithelial cell indicators levels considerably rose." (PMID 38347836, 2024). "In order to examine whether TBL1XR1 protein was overexpressed in gastric cancer, immunohistochemistry staining was performed in 334 GC tissues, 30 corresponding lymph node metastasis lesions, and 20 adjacent nontumor mucosa tissues." (PMID 27672238, 2016). "By stimulating the ERK1/2 signaling pathway, TBL1XR1 controls EMT process, cell migration, cell invasion, and cell proliferation of gastric cancer cells." (PMID 38347836, 2024). "TBL1XR1 overexpression increased spheroid formation and upregulated Sox2 and CD44 expression in gastric cancer cells." (PMID 38347836, 2024). "The majority of TBL1XR1 was found in the nucleus of tumor cells in ovarian cancer, ESCC, NPC, gastric cancer in patient tissues." (PMID 38347836, 2024). "TBL1XR1 is recognized as the prognostic marker of NSCLC and is found to be related to gastric, breast, and stomach cancers." (PMID 35885958, 2022). "This present study demonstrates that TBL1XR1 is overexpressed in gastric cancer and may be a potential predictor and therapeutic target for GC patients." (PMID 27672238, 2016). "In NSCLC and gastric cancer, lack of TBL1XR1 expression eliminated cell migration and invasion, whereas forced TBL1XR1 expression enhanced cell migration and invasion." (PMID 38347836, 2024).
Pierpont syndrome (9 papers, 2016 to 2025). "According to the OMIM database, variants in TBL1XR1 are associated with Pierpont syndrome (PS; OMIM: 602342)." (PMID 41444645, 2025). "Further, the subjects diagnosed with Pierpont Syndrome carried variants in TBL1XR1 beyond those that had been previously reported in association with Pierpont Syndrome." (PMID 38378692, 2024). "These include motor coordination, memory skills, and social impairments, which are described at different levels in patients with TBL1XR1 deletions, missense mutation, and Pierpont syndrome." (PMID 33708771, 2021). "In conclusion, one specific TBL1XR1 missense mutation is responsible for the phenotype in individuals with Pierpont syndrome." (PMID 26769062, 2016). "A heterozygous missense mutation in TBL1XR1 has also been found to cause Pierpont Syndrome, a condition associated with distinctive craniofacial features, global developmental delay, epilepsy, and neurodevelopmental disorders including attention-deficit hyperactivity disorder." (PMID 41012410, 2025). "The variants of TBL1XR1 are associated with Pierpont syndrome (PS) and developmental delay (DD)." (PMID 41444645, 2025). "In contrast to the prior literature linking Pierpont Syndrome to a small number of specific missense variants in TBL1XR1, individuals in this survey received the diagnosis associated with a wide array of genetic variants in TBL1XR1, including other missense variants, premature truncation, and CNV." (PMID 38378692, 2024). "Patient #22 carried a de novo variant in TBL1XR1 that recently has been associated with Pierpont syndrome but was classified as a gene of unknown significance at the time of the first report." (PMID 30091983, 2018). "Because WDSTS can phenotypic overlap with Pierpont syndrome, Cornelia De Lange syndrome and Kabuki syndrome, the candidate genes causing the later three syndromes (i.e. TBL1XR1, NIPBL, SMC1A, SMC3, RAD21, HDAC8, KMT2D, and KMD6A) in our cohort have been excluded." (PMID 30305169, 2018). "This study identifies a specific TBL1XR1 mutation as the cause of Pierpont syndrome." (PMID 26769062, 2016). "Further study is needed, but this raises the possibility that features of Pierpont Syndrome can be seen more broadly with other changes in the TBL1XR1 gene." (PMID 38378692, 2024). "Of these, nine respondents (21.9%) did not provide genetic information and were included due to a self-reported diagnosis of TBL1XR1-related disorder or Pierpont Syndrome." (PMID 38378692, 2024). "Altogether, these results suggest that Tbl1xr1 mutant mice are mildly microcephalic, as seen in particular in Pierpont syndrome patients, and that their excitatory synapses are hyperactive." (PMID 33708771, 2021). "The phenotypic spectrum of TBL1XR1-related disorder, however, extends beyond Pierpont Syndrome." (PMID 38378692, 2024). "In this study, we found a single TBL1XR1 missense mutation in six patients with Pierpont syndrome that was absent in their unaffected parents." (PMID 26769062, 2016). "TBL1XR1 mRNA expression was well visible in the pituitary and the PVN area of the hypothalamus, as well as in liver and muscle tissue and both white and brown adipose tissue, fitting the clinical symptomatology of Pierpont syndrome." (PMID 26769062, 2016).